PGR (progesterone receptor)
Diseases named in the same sentence as PGR in open-access papers (continued):
Sharing a sentence is not in itself a finding about the gene and the disease.
invasive breast carcinoma (116 papers, 2002 to 2026). A carcinoma that infiltrates the breast parenchyma. "So far, few biomarkers have been well recognized in invasive breast carcinomas, including estrogen receptor (ER) and progesterone receptor (PR), which are associated with a better outcome and are predictive of endocrine sensitivity." (PMID 32085795, 2020). "We confirmed an association between TBX3 and estrogen receptor (ER) and progesterone receptor (PR) expression in invasive breast cancers, which has been suggested by previous studies." (PMID 30697731, 2019). "An immunohistochemistry-based analysis of specimens from over 1,300 invasive breast cancer patients also revealed a significant association with advanced tumour stage, grade, size, oestrogen and progesterone receptor status." (PMID 23874748, 2013). "In addition, reduced expression of YAP in invasive carcinoma is associated with estrogen receptor α (ERα) and progesterone receptor (PR) negativity in invasive breast carcinomas." (PMID 25811979, 2015). "Furthermore, parity was negatively associated with the risk of estrogen receptor-positive (ER+) or ER+/progesterone receptor-positive (PR+) while age at first full-term pregnancy was positively associated with the risk of ER+ or ER+/PR+ invasive breast cancer." (PMID 20565829, 2010). "A core needle biopsy demonstrated invasive mammary carcinoma that was estrogen receptor-positive, progesterone receptor-positive, and human epidermal growth factor receptor 2 (HER2)-negative." (PMID 41728528, 2026). "Estrogen and progesterone receptor-positive tumors account for 70% of invasive breast cancers while TNBC constitutes 10% of invasive breast cancers." (PMID 33499000, 2021). "Based on this retrospective study, histological markers of 113 individuals sufferingfrom invasive breast cancer -such as estrogen receptor (ER), progesterone receptor,HER-2 receptor, E-cadherin, CK5/6, vimentin and Ki67 were examined byIHC technique." (PMID 31210439, 2019). "According to the National Comprehensive Cancer Network (NCCN) guideline, patients with invasive breast cancer who are ERα-positive or progesterone receptor (PR)-positive are eligible for tamoxifen, the selective estrogen receptor modulator (SERM)." (PMID 30208932, 2018). "For decades, samples of patients diagnosed with invasive breast carcinomas were sent to laboratories equipped with immunohistochemical techniques in the developed countries for ER and PgR examination." (PMID 28173783, 2017). "ACC in breast tissues constitutes ~1% of all invasive breast cancers and is categorized as triple-negative for estrogen receptor (ER), progesterone receptor (PR), and human epidermal growth factor receptor 2 (HER2)." (PMID 27213588, 2016). "The majority of invasive breast cancers express the estrogen receptor (ER) and/or progesterone receptor (PR), predicting a greater likelihood of response to hormone therapy." (PMID 26728744, 2016). "An approximation of the gene expression based subtypes using immunohistochemical (IHC) detection of HER2, estrogen receptor- (ER) and progesterone receptor (PR) expression has been suggested for invasive breast cancer." (PMID 26062614, 2015). "Triple negative breast carcinomas (TNBC) are invasive breast carcinomas that lack expression of estrogen receptor (ER), progesterone receptor (PR) and human epidermal growth factor receptor 2 (HER2)." (PMID 25506917, 2014). "We classified 5,687 invasive breast cancers by molecular subtype based on immunohistochemical expression of estrogen-receptor (ER), progesterone-receptor (PR), human epidermal growth factor receptor 2 (HER2), and Ki-67 proliferation index." (PMID 25174527, 2014). "Tumor data on 531 invasive breast cancer cases subtyped by estrogen receptor, progesterone receptor and human epidermal growth factor receptor 2 (Her2) status were obtained [luminal A, luminal B, triple-negative (TN) and Her2-type]." (PMID 23181105, 2012).
invasive breast carcinoma (continued). "In the present study, we compared the results from ER and PgR testing on 500 invasive breast carcinomas between a reference laboratory and 146 different local laboratories in Brazil." (PMID 21971899, 2011). "As previously presented, 255 invasive breast carcinomas samples were tested for ER and PgR for validation purposes." (PMID 21971899, 2011). "Tumor tissue microarrays, representing 4,049 cases of invasive breast cancers with 20 years of follow up, were subtyped by the expression profiles of estrogen receptor, progesterone receptor, or HER-2." (PMID 18925950, 2008). "Uehara evaluated estrogen and progesterone receptor positivity in invasive breast carcinoma in women receiving tamoxifen at a dose of 20 mg/day for two and 14 days." (PMID 16972993, 2006). "Preoperative core biopsy is highly sensitive for the IHC detection of ER and PgR in invasive breast cancer." (PMID 16115314, 2005). "This retrospective study examines the correlation between CNB and surgical excision in regards to the ER ad PgR status of invasive breast cancer using IHC." (PMID 16115314, 2005). "In summary, preoperative CNB is highly sensitive for the IHC detection of ER and PgR in invasive breast cancer." (PMID 16115314, 2005). "In addition, assessing the expression of estrogen receptor (ER), progesterone receptor (PgR), and Her-2/neu has facilitated targeted therapy in invasive breast carcinoma (IBC)." (PMID 36247496, 2022). "Hormone-receptor (that is, estrogen receptor [ER] and progesterone receptor [PR]) testing is recommended for all invasive breast cancers, as this predicts which patients may benefit from adjuvant endocrine therapy." (PMID 33910628, 2021). "Standard specimen reporting guidelines from the College of American Pathologists (CAP; 2021) recommend biomarker analysis on diagnostic biopsies, including estrogen receptor (ER), progesterone receptor (PR), and human epidermal growth factor receptor-2 (HER2), for invasive breast carcinomas." (PMID 34898544, 2021). "A nested case-control study was established within the European Prospective Investigation into Cancer cohort, which included 1624 first primary incident invasive breast cancer cases (with known estrogen and progesterone receptor and HER2 status) and 1624 matched controls." (PMID 31547832, 2019). "Receiver operator characteristic curves revealed that the prognostic value of miR-320a was enhanced when compared with the widely used prognostic biomarkers (estrogen receptor, progesterone receptor and human epidermal growth factor-2) in invasive breast cancer." (PMID 25120655, 2014). "Tumor data on 2544 invasive breast cancer cases subtyped by estrogen receptor, progesterone receptor, and human epidermal growth factor receptor 2 (Her2) status were obtained (1868 luminal A tumors, 294 luminal B tumors, 288 triple-negative tumors and 94 Her2-overexpressing tumors)." (PMID 19463150, 2009). "The objective of this study was to determine the concordance rate between core needle biopsy (CNB) and surgical excision of invasive breast cancer regarding the oestrogen receptor (ER) and Progesterone receptor (PgR) status as determined by Immunohistochemistry (IHC)." (PMID 16115314, 2005). "IBC: invasive breast cancer; DCIS: ductal carcinoma in situ; ER/PR: estrogen receptor/progesterone receptor; HER2: human epidermal growth factor receptor 2; OR: odds ratio; CI: confidence interval; FET: Fisher’s exact test; X2: Chi-square test." (PMID 40519488, 2025). "Estrogen receptor (ER), progesterone receptor (PR), HER2 and Ki67 are the most useful immunohistochemical biomarkers of invasive breast cancer." (PMID 40336872, 2023). "Accurate assessment of estrogen receptor (ER), progesterone receptor (PgR), human epidermal growth factor receptor-2 (HER2) status and Ki-67 proliferative index were the key-point to tailor invasive breast cancer treatment." (PMID 37823052, 2023).
invasive breast carcinoma (continued). "Particularly, lesion expression of the estrogen receptor (ER), progesterone receptor (PR), HER2 and Ki-67 have been identified as promising biomarkers to monitor the progression of invasive breast cancers in humans." (PMID 35804497, 2022). "HER2-positive BrCa, defined as ER−/PgR−/HER2+, accounts for 10% to 34% of all invasive breast cancers." (PMID 35158842, 2022). "Estrogen receptor (ER), progesterone receptor (PgR), Ki-67, and HER2 immunohistochemistry (IHC) together with HER2 in situ hybridization (ISH) are utilized to classify invasive breast cancer (IBC) into predictive molecular subtypes." (PMID 34572945, 2021). "Estrogen receptor (ER), progesterone receptor (PR), human epidermal growth factor (HER2), and Ki67 levels are the basis for defining the intrinsic molecular subtypes of invasive breast cancer." (PMID 33102239, 2020). "Gene-level quantifications from RNA-Seq data of 1246 invasive breast cancer samples from The Cancer Genome Atlas were clustered based on their expression of HER2, ESR1, and PGR." (PMID 30279965, 2018). "TNBCs characterized by negativity for estrogen receptor (ER), progesterone receptor (PR), and HER-2 genes, represent 10%–24% of invasive breast cancers." (PMID 28230773, 2017). "The aim of our study was to compare the estrogen receptor, progesterone receptor and HER2 status as determined by the MapQuantTM test to the routine immuno-histochemical tests in early stage invasive breast cancer in a large comprehensive cancer center." (PMID 26829108, 2016). "National Comprehensive Care Network guidelines for adjuvant treatment of invasive breast cancer are based on HER2 and hormone receptor (HR) status, where HR+ disease encompasses all estrogen receptor (ER)+ and/or progesterone receptor (PR)+ tumors." (PMID 27250116, 2016). "Our results show that the MapQuantTM assay, based on mRNA expression assay, provides an objective and quantitative assessment of Estrogen receptor, Progesterone receptor and HER2 status in invasive breast cancer." (PMID 26829108, 2016). "In conclusion, our results show that the MapQuant assay, based on mRNA expression assay, provides an objective and quantitative assessment of Estrogen receptor, Progesterone receptor and HER2 status in invasive breast cancer." (PMID 26829108, 2016). "In this study, using an immunohistochemical method, 272 patients with invasive breast cancer were assessed for the expression of CHIP (graded scores 0‐3) and the statuses of biomarkers, such as estrogen receptor (ER), progesterone receptor (PgR), and HER2." (PMID 27334118, 2016). "The status of the expression of the estrogen receptor (ER), progesterone receptor (PR), and human epidermal growth factor receptor 2 (HER2) are the most important prognostic markers for invasive breast cancer." (PMID 25200065, 2014). "Triple-negative or basal-type carcinomas account for 15% of all invasive breast cancers and are characterized by lack of ER, progesterone receptor (PR), and HER2 expression." (PMID 40725750, 2025). "A subgroup of invasive breast cancer that is positive for human epidermal growth factor receptor 2 is ER- and progesterone receptor (PR)-negative, and represents about 15% of all invasive breast cancers." (PMID 39203926, 2024). "In invasive breast cancer of no special type, high STING expression was linked to estrogen receptor (ER) and progesterone receptor (PR) expression (p < 0.0001 each), non-triple-negative status (p = 0.0028), and poor overall survival (p = 0.0196)." (PMID 39001487, 2024). "TNBC is a heterogeneous subgroup of invasive breast carcinomas characterized by the lack of ER, progesterone receptor, and HER2." (PMID 39338195, 2024).
invasive breast carcinoma (continued). "Triple-negative breast cancer (TNBC) is characterized by the lack of three key molecular signatures: estrogen receptor (ER) expression, progesterone receptor (PR) expression, and HER2 overexpression; it comprises approximately 15% of all invasive breast cancers." (PMID 38268032, 2024). "This cross-sectional study assesses the proportion of female patients with invasive breast cancer who have no record of testing for estrogen receptor, progesterone receptor, or ERBB2 status." (PMID 37615986, 2023). "This case report describes a 56-year-old female with invasive breast cancer without estrogen or progesterone receptor expression, with apocrine differentiation, and with no germline variants in the BRCA1 and BRCA2 genes." (PMID 37583932, 2023). "According to the assessment of immunohistochemistry (IHC), the expression of estrogen receptor (ER), progesterone receptor (PR), and human epidermal growth factor receptor 2 (HER2) was found to be 80%, 60–70%, and 15–20%, respectively, in all invasive breast carcinomas." (PMID 36831369, 2023). "Triple-negative breast carcinomas (TNBCs) are invasive breast carcinomas lacking oestrogen receptor (ER) or progesterone receptor (PR) expression and HER2 amplification." (PMID 34458945, 2022). "This work outlines the literature on biological assessment outside of standard biomarkers (defined as ER, PgR, HER2, Ki67) in women ≥ 65 years with primary operable invasive breast cancer, to determine which additional biomarkers are relevant to outcome in older women." (PMID 34165702, 2021). "These heterogeneous tumors comprise 12–17% of all invasive breast cancers (BCa) and are characterized by lack of expression of estrogen receptor (ER), progesterone receptor (PR) and absence of HER2/neu overexpression or gene amplification." (PMID 32850312, 2020). "Pathological examination showed bilateral, grade 3 invasive breast carcinoma (no special type) with ER, progesterone receptor (PR) and HER2 negativity by immunohistochemistry (IHC) and fluorescence in situ hybridization (FISH)." (PMID 32611325, 2020). "Approximately 15% of invasive breast cancers are triple-negative breast cancers (TNBC) that lack estrogen receptor (ER), progesterone receptor (PR), and human epidermal growth factor receptor 2 (HER2) expressions and usually exhibit a high pathological grade and more aggressive clinical behavior." (PMID 27833085, 2016). "Line correlation analysis was used to evaluate the correlation between an immunohistochemical panel of estrogen receptor (ER), progesterone receptor (PR), human epidermal growth factor receptor 2 (HER2) and Ki-67, and ALDHhiCD44+ cells from patients with invasive breast carcinoma." (PMID 25789008, 2015). "The tumor was an infiltrating breast carcinoma of the right breast, and was estrogen receptor-positive, progesterone receptor-negative and Her2/neu-negative, without any lymph node metastasis." (PMID 25683334, 2015). "Routinely processed paraffin sections of hormone receptor-negative ductal invasive breast cancer were stained for estrogen and progesterone receptor by immunohistochemistry." (PMID 25565114, 2014). "Clinically, hormonal therapy is not used in the treatment of ER/PgR-negative invasive breast cancer and chemoprevention has not had demonstrated to be of benefit in ER/PgR-negative invasive breast cancer or ER/PgR-negative DCIS." (PMID 22091428, 2011). "The current study was undertaken to investigate the hormonal receptor status of DCIS of the breast in patients with ER/PgR-negative invasive breast cancer." (PMID 22091428, 2011).
invasive breast carcinoma (continued). "A three-step immunohistochemical method was applied to paraffin-embedded sections from 154 patients with invasive breast carcinoma in order to detect expressions of the proteins EGFR, pEGFR, oestrogen receptor, progesterone receptor, c-erbB-2, pAkt, VEGFR-1/Flt-1, MMP-14 and uPAR." (PMID 18522728, 2008). "Core needle biopsy was taken from the lump in the nine o'clock position, which showed invasive breast carcinoma of no special type, grade I, estrogen receptor (ER) 2+ positivity in 60% of tumor cells (Allred score = 6/8), progesterone receptor (PR) negative, HER2/neu negative, with Ki-67 of 5%." (PMID 41267721, 2025). "Among the invasive breast cancer cases, 1.2% lacked information on tumour size, 0.3% on lymph nodes status, 6.4% on distant metastasis status, 10% on histological grade, 2.9% on ER status, 3.1% on PgR status, 22% on HER2 and 37% on Ki-67." (PMID 38454634, 2024). "Among 1139 evaluable invasive breast carcinomas of NST, low or absent mammaglobin-A immunostaining was linked to a high BRE grade (p = 0.0011), loss of estrogen receptor and progesterone receptor expression, and triple-negative status (p < 0.0001 each) but not to overall survival." (PMID 36980510, 2023). "However, 20% of invasive breast cancers exhibit discordant hormone receptor statuses, and most are ER-positive/PgR-negative subgroups." (PMID 37684569, 2023). "Among 1139 evaluable invasive breast carcinomas of no special type, low mammaglobin-A immunostaining was linked to high BRE grade (p = 0.0011), loss of estrogen and progesterone receptor expression (p < 0.0001 each), and triple-negative status (p < 0.0001) but not to patient survival." (PMID 36980510, 2023). "Triple-negative breast cancer (TNBC) is characterized by a subtype of invasive breast cancer that does not express three important molecular markers including estrogen receptor (ER), progesterone receptor (PR) and human epidermal growth factor receptor 2 (HER-2)." (PMID 34836197, 2021). "In particular, the TNBC phenotype (ER/PgR/HER2–negative), which accounts for 10-24% of invasive breast cancers, is characterized by earlier onset, poor prognosis, and limited therapeutic options, therefore, it may represent a priority epidemiological research target." (PMID 25413873, 2014). "CNB was accurate in determining ER, PgR, and HER2 status as well as non-Luminal molecular subtypes in invasive breast cancer." (PMID 23957561, 2013). "This patient was diagnosed with an invasive breast cancer in the upper outer quadrant of the right breast (TNM: pT1c pN0(sn) M0; estrogen and progesterone receptor expression positive; MIB1 25%; Her2/neu negative) and received breast conserving surgery in December 2015." (PMID 35884579, 2022). "Although progesterone receptor (PR) was assessed for invasive and not DCIS cases, it was uncommon for invasive breast cancer in the CBCS to be PR positive and ER negative and therefore differentiation between subgroups of hormone receptor positive cancers was not possible." (PMID 30682163, 2019). "Triple-negative breast cancer (TNBC) (tumors that do not express estrogen receptor (ER) and progesterone receptor (PR) genes and with nonoverexpressed/nonamplified HER-2 gene) accounts for 10%–24% of invasive breast cancers, and it is typically high-grade tumor with different histological types." (PMID 26504780, 2015).